ARHGEF11 (Rho guanine nucleotide exchange factor 11)
Description:
May play a role in the regulation of RhoA GTPase by guanine nucleotide-binding alpha-12 (GNA12) and alpha-13 (GNA13). Acts as guanine nucleotide exchange factor (GEF) for RhoA GTPase and may act as GTPase-activating protein (GAP) for GNA12 and GNA13. Involved in neurotrophin-induced neurite outgrowth.
Synonyms: KIAA0380; GTRAP48; PDZ-RHOGEF
Tractability: Small molecule: a structure with a bound ligand is known. Antibody: its Gene Ontology location is reachable by antibodies, with high confidence; the Human Protein Atlas places it where antibodies can reach. PROTAC: UniProt records ubiquitination sites on it; ubiquitination databases record sites on it; its protein half-life has been measured.
Gene: Protein-coding gene on chromosome 1 (156,934,840 to 157,046,903, reverse strand). Ensembl gene ENSG00000132694.
Subcellular location: Cytoplasm; Membrane
Subcellular location (Human Protein Atlas): Plasma membrane; Nucleoplasm
Pathways (Reactome):
Signal Transduction: CDC42 GTPase cycle; G alpha (12/13) signalling events; NRAGE signals death through JNK; RAC1 GTPase cycle; RHOA GTPase cycle; RHOB GTPase cycle; RHOC GTPase cycle
Developmental Biology: Sema4D induced cell migration and growth-cone collapse
Gene Ontology:
Molecular function: G protein-coupled receptor binding; protein binding; guanyl-nucleotide exchange factor activity
Biological process: G protein-coupled receptor signaling pathway; positive regulation of DNA-templated transcription; Rho protein signal transduction; actin cytoskeleton organization; establishment of cell polarity; regulation of cell growth; regulation of small GTPase mediated signal transduction; striated muscle contraction
Cellular component: cytoplasm; plasma membrane; cytosol; membrane
Genetic constraint (gnomAD): Loss-of-function variants: 52 observed, 195.2 expected, observed/expected ratio (o/e) 0.27, 90% interval 0.21 to 0.34. The upper end of that interval is the gene's LOEUF score, 0.34, which puts it in group 1 of 6, group 1 being the genes least tolerant of losing a copy. Missense variants: 1,719 observed, 2,063.7 expected, observed/expected ratio (o/e) 0.83, 90% interval 0.8 to 0.87. Synonymous variants: 693 observed, 788.72 expected, observed/expected ratio (o/e) 0.88, 90% interval 0.82 to 0.94.
Homologues: Orthologues: chimpanzee ARHGEF11 (99% identical), macaque ARHGEF11 (98% identical), rabbit ARHGEF11 (90% identical), pig ARHGEF11 (89% identical), dog ARHGEF11 (86% identical), mouse Arhgef11 (85% identical), guinea pig ARHGEF11 (85% identical), rat Arhgef11 (83% identical), tropical clawed frog arhgef11 (61% identical), zebrafish arhgef11 (23% identical), Drosophila melanogaster cyst (13% identical), Caenorhabditis elegans prhg-1 (10% identical). Paralogues in human: ARHGEF12 (31% identical), ARHGEF1 (21% identical), ARHGEF28 (15% identical), ARHGEF18 (12% identical), ARHGEF2 (11% identical), NET1 (8% identical), PLEKHG6 (8% identical), ARHGEF3 (7% identical).